INS (insulin)
Diseases named in the same sentence as INS in open-access papers (continued):
Sharing a sentence is not in itself a finding about the gene and the disease.
Insulin resistance (continued). "Insulin resistance (IR) is defined as the inability of a known quantity of insulin to increase glucose uptake and utilization in target tissues and organs, as much as it does in a normal physiological status." (PMID 34734480, 2021). "As insulin inhibits lipolysis, insulin resistance leads to increased circulating free fatty acids, which in turn fuels and exaggerates the insulin resistance tightly correlated with hypertension and CVDs at the core of CMS." (PMID 33897419, 2021). "In this study, we observed higher waist circumference, greater level of insulin, insulin resistance, and androgen in individuals with classic phenotype of PCOS." (PMID 33750349, 2021). "These include, among others, systemic inflammation promoted by endotoxin through Toll-like receptor (TLR) binding, increased insulin secretion, and insulin resistance." (PMID 34684657, 2021). "In PCOS women, the excess of androgens impairs hepatic glucose metabolism by decreasing insulin-stimulated glucose uptake and glycogen synthesis, thus predisposing PCOS women to insulin resistance." (PMID 34572151, 2021). "The insulin resistance in PCOS is usually resulted from abnormal insulin signalling, metabolic dysfunction in insulin-responsive tissues, and importantly, the increased volume of fat tissues." (PMID 33910166, 2021). "Insulin resistance refers to the dysfunction of insulin in facilitating glucose assimilation and utilization for various reasons, leading to excessive compensatory secretion of insulin to maintain the stability of blood glucose." (PMID 34489866, 2021). "In accordance with our results, we observed that overexpression of mHtt in neuronal cells markedly blocks insulin signaling and results in a condition similar to insulin resistance." (PMID 34445125, 2021). "GDM is characterized by β-cell dysfunction, insulin secretory defect and peripheral insulin resistance." (PMID 34633445, 2021). "Historically, the term insulin insensitivity (synonymous with insulin resistance) was used to define the relatively poor glucose response to exogenous insulin exhibited by obese diabetic patients." (PMID 33810179, 2021). "Summary of fluorine-labelled fluorodeoxyglucose ([18F]-FDG) studies evaluating the effect of Alzheimer’s disease (AD), mild cognitive impairment (MCI), aging, obesity, and insulin resistance (IR) on brain glucose metabolism during fasting and insulin clamp #." (PMID 33917464, 2021). "For instance, in metabolic tissues, GLUT4 potentiates insulin-mediated glucose uptake and reduced GLUT4 levels correlate with hyperglycaemia and insulin resistance in insulin-responsive tissues, as seen in Brn-3b KO mice." (PMID 33712567, 2021). "Type 2 diabetes (T2D) develops in people with insulin resistance, when the pancreatic β-cell becomes unable to produce sufficient insulin to compensate for the decreased insulin sensitivity." (PMID 34444964, 2021). "Fasting glucose levels remain normal as long as insulin hypersecretion can compensate for insulin resistance." (PMID 34746307, 2021). "The insulin-stimulated glucose uptake was twice higher in adipocytes with the previously developed insulin resistance treated with 1,2-diCA-PC than in control adipocytes with proper insulin sensitivity." (PMID 34684619, 2021). "The frequency of increased fasting serum insulin, indicating insulin resistance, was significantly higher in the controls compared to athletes (n=10 (9%) vs n=0 (0%), p <0.01)." (PMID 34484121, 2021). "IL-17 is one of the central molecules of the Th17/IL-23 axis that interferes with hepatic steatosis in nonalcoholic fatty liver disease (NAFLD), and insulin signalling and IL-17R expression correlate with insulin resistance." (PMID 34207504, 2021). "Many researchers have identified that the phosphorylated JNK negatively regulates the insulin signaling pathway and simultaneously leads to insulin resistance." (PMID 33672590, 2021).
Insulin resistance (continued). "Whole-body insulin resistance (IR) reflects defective insulin action in tissues such as skeletal muscle, liver, adipose tissue, gut and brain, and is a major risk factor for T2DM and CVD." (PMID 34277687, 2021). "In such condition, the development of insulin resistance is a feature; however, some studies have suggested that haploinsufficiency of X-chromosome gene(s) can also impair insulin secretion." (PMID 33430527, 2021). "In order to determine the effect of deletion of PRAK on insulin resistance, we implemented glucose tolerance tests and insulin tolerance tests." (PMID 34360761, 2021). "In this cross-sectional analysis of a selenium-replete population of US adults, blood selenium concentration was positively associated with insulin concentration and HOMA-IR, markers of insulin resistance." (PMID 34262926, 2021). "Our findings indicated that although the insulin resistance appeared to have been corrected, the ability to secrete insulin decreased with each passing generation." (PMID 34209784, 2021). "Metformin is an insulin sensitizer since it enhances signaling through the insulin receptor, leading to an improvement in insulin resistance, followed by a decrease in circulating insulin levels." (PMID 34682906, 2021). "Another often used surrogate index of hepatic insulin resistance (i.e., the reverse of insulin sensitivity) is the homeostasis model assessment of insulin resistance (HOMA-IR) calculated from plasma glucose and insulin concentrations in the fasting state." (PMID 33498493, 2021). "Firstly, thyroid hormone plays an important role in insulin signaling pathway.The level of FT3 and FT4 has been reported to be negatively associated with insulin resistance index (HOMA-IR), while TSH was positively associated with HOMA-IR." (PMID 34017311, 2021). "Insulin resistance, defined as a defect in the capacity of insulin to drive glucose to its target tissue, is one of the major characteristics of T2D." (PMID 34434893, 2021). "One study that compares Brazilian communities with different levels of urbanization demonstrated that urban dwellers had higher BMI and higher levels of insulin, fasting glucose, and insulin resistance." (PMID 35153809, 2021). "In insulin resistance, which reportedly affects more than 32.2% of the population in the United States, the cells stop responding to insulin." (PMID 34641407, 2021). "The physiological significance of PP2A and its involvement in insulin signalling have been revealed by the findings that PP2A deletion leads to insulin hypersensitivity but PP2A overexpression induces insulin resistance." (PMID 34208786, 2021). "Insulin resistance refers to an impairment in the biological effects of insulin on target tissues, such as the ability to promote glucose uptake and inhibit the breakdown of glycogen in adipocytes and skeletal muscle cells." (PMID 33816504, 2021). "Subjects with T2DM showed decreased Disposition index (reflecting the ability of pancreas to secrete insulin accordingly to prevalent Insulin resistance) by 23% and 201% increased Insulin resistance compared with healthy control subjects." (PMID 33574418, 2021). "For example, in skeletal muscle inhibiting nitric oxide production in response to insulin diminishes microvascular perfusion and decreases insulin-stimulated glucose uptake, i.e., contributes to metabolic insulin resistance." (PMID 34299190, 2021). "The effect of the HFD on body weight, fat pad mass, liver weight, liver lipid content, and insulin resistance in our study occurred later than in other studies in which HFD feeding impaired insulin sensitivity earlier." (PMID 34948432, 2021). "While, T2DM is characterized by several disorders, such as impaired insulin secretion, insulin resistance (e.g., in muscles, liver, and adipose), and excessive secretion of glucagon-like-peptide-1." (PMID 33669379, 2021).
Insulin resistance (continued). "Injection of recombinant FGF-21 in obese mice successfully ameliorated hepatic steatosis, glucose intolerance, and insulin resistance through increased insulin production and secretion." (PMID 33537089, 2021). "The presented data collectively indicate that vaspin plays a protective mechanism in obesity, characterized as a chronic inflammation connected to insulin resistance by its insulin-sensitizing and anti-inflammatory effects." (PMID 34359881, 2021). "PHQ-9 scores correlated positively with total and acylated ghrelin and with WHR, insulin, glucose, and homeostasis model assessment of insulin resistance (HOMA-IR)." (PMID 33674672, 2021). "IGFBP2 was an independent predictor of insulin sensitivity, which suggests that IGFBP2 plays a central role in the insulin/IGFs system crosstalk and it is closely linked to insulin resistance." (PMID 33498859, 2021). "Activators of both PPARα and PPARγ have been shown to improve insulin sensitivity and normalize impaired glucose tolerance in both humans and rodent models of insulin resistance." (PMID 34899310, 2021). "Subjects with increased CAP value tend to be older and have higher BMI, waist and neck circumferences, waist-to-hip ratio, triglyceride, uric acid, fasting insulin, white blood cell count, and insulin resistance indices, whereas lower adiponectin and eGFR." (PMID 35173677, 2021). "There was a significant reduction in insulin resistance, fasting blood glucose, and fasting serum insulin with an increase of insulin sensitivity and β cell function." (PMID 34576959, 2021). "We find that the HNF1A mutation results in a loss of binding and decreased expression of genes involved in pancreas development, β cell survival, insulin secretion, insulin resistance and type 2 diabetes (T2D)." (PMID 34035238, 2021). "Insulin resistance is a metabolic disorder resulting in wide-ranging effects on many organs and insulin-regulated pathways." (PMID 34394128, 2021). "Resistin and adiponectin are antagonist molecules, since resistin induces insulin resistance and is considered pro-inflammatory, whereas adiponectin induces insulin sensitivity and is considered protective against inflammation." (PMID 34822574, 2021). "Ipra treatment suppressed the increase of UAE in HFD-fed mice, decreased serum insulin levels, and improved insulin resistance." (PMID 34298949, 2021). "In patients with obesity and T2D, increased levels of succinate correlate with increased BMI, insulin, glucose, insulin resistance, and triglycerides." (PMID 34943862, 2021). "Insulin resistance and insulin sensitivity will be determined using the HOMA-IR and QUICKI equations." (PMID 34593030, 2021). "Excess insulin-induced insulin resistance has been demonstrated in several hypothalamic neuronal models, including NPY/AgRP- and POMC-expressing neurons." (PMID 34831343, 2021). "These volunteers were also mildly insulin resistant, based on the HOMA-IR scores calculated from the reported average baseline insulin and glucose values (calculated 2.0; scores > 1.9 are mildly insulin resistant)." (PMID 34220427, 2021). "The treatment with PSTi8 increases insulin sensitivity in db/db, high fat and fructose-fed streptozotocin-induced insulin resistance mice." (PMID 34204153, 2021). "There are some reports that elevated insulin levels/hyperinsulinemia alone can precipitate insulin resistance and obesity, thus making the lower insulin levels in the Met + HFD PN of potential benefit." (PMID 34977118, 2021). "Insulin resistance occurs when insulin is unable to sufficiently stimulate glucose uptake in muscle and inhibit hepatic glucose production." (PMID 34336862, 2021). "To further confirm the effect on insulin resistance, we measured the serum insulin and calculated HOMA-IR." (PMID 33668369, 2021). "The homeostasis model assessment of insulin resistance (HOMA-IR) is frequently used in the clinical setting but also has limited applicability because insulin levels must be measured." (PMID 34735502, 2021).
Insulin resistance (continued). "Probiotic supplements can improve insulin level, β-cell function, insulin resistance, and insulin sensitivity, especially in healthy pregnant women or those with GDM in this study." (PMID 34603479, 2021). "Insulin resistance decreases the sensitivity of tissue to the presence of insulin and plays a major role in the development of many metabolic health disorders in humans, including obesity, type 2 diabetes, hypertension, and cardiovascular disease." (PMID 34438693, 2021). "During insulin resistance, insulin is unable to inhibit hepatic glucose production, and consequently blood glucose levels rise." (PMID 34336862, 2021). "EVs are membrane-enclosed envelopes that carry proteins, lipids, miRNAs, and other factors, which appear to interfere with insulin signaling, promoting insulin resistance." (PMID 34440850, 2021). "In terms of insulin resistance, NNRTIs were found to reduce insulin sensitivity through its pro-inflammatory effects." (PMID 34769448, 2021). "Periodontitis can lead to type 1 diabetes by mediating decrease in insulin release and insulin resistance through cytokines alteration." (PMID 34113341, 2021). "We used a combination of TNF-α, insulin, and glucose for insulin resistance, and BSA-palmitate to treat cultured primary hippocampal and cortical neurons." (PMID 33859286, 2021). "FAF1 mediated hepatic metabolic disorder via interaction with JNK and impairment of the insulin signaling pathway, thereby leading to aggravated glucose metabolism disorder, lipid metabolism disorder, and insulin resistance." (PMID 33510836, 2021). "Muscle insulin resistance accounts for more than 80% of the impairment in total body glucose disposal in T2D patients and is often characterized by an impaired insulin signaling." (PMID 33566837, 2021). "It is noteworthy that there was a high coherence between the two variables of insulin and insulin resistance (p < 0.001 and r = 0.901); therefore, the independent variable of insulin was replaced with resistance to insulin." (PMID 33747570, 2021). "Decreased hepatic insulin clearance usually results in increased insulin secretion to compensate for insulin resistance." (PMID 33972568, 2021). "The excessive amount of weight in obese patients is correlated with insulin resistance in different tissues, compensated for by the stimulation of pancreatic insulin secretion that leads to chronic hyperinsulinemia." (PMID 34684639, 2021). "Despite demonstrating that HFD-mice developed whole-body insulin resistance (measured by increased glucose infusion rate during hyperinsulinemic-euglycemic clamps), insulin suppressed autophagy in both groups to the same extent." (PMID 34336862, 2021). "The main predictor of NAFLD is hepatic insulin resistance, defined by the failure of insulin to suppress endogenous glucose production, e.g., gluconeogenesis." (PMID 34359991, 2021). "Pancreatic β cells proliferate in the islets of Langerhans during pregnancy to increase insulin secretion in response to insulin resistance." (PMID 33776619, 2021). "Reductions in BCAAs and AAAs correlate with improved insulin sensitivity, as estimated by hyperinsulinemic–euglycemic clamp or homeostatic model assessment of insulin resistance (HOMA-IR)." (PMID 34445047, 2021). "Insulin resistance (IR) means the reduced sensitivity or reactivity of tissues to insulin-mediated biologic activity that leads to high glucose levels and represents the major risk factor of prediabetes and T2DM." (PMID 34099024, 2021). "TMAO supplements in high fat diet fed mice modeling insulin resistance and inflammation demonstrated elevated fasting insulin levels and reduced insulin signaling cascade expression along with increased inflammation markers." (PMID 34445033, 2021). "The mechanism of insulin resistance is not limited to impaired insulin signaling, but it also involves the complex interplay of multiple metabolic pathways." (PMID 33681089, 2021).
Insulin resistance (continued). "Inordinately large amounts of insulin are required to achieve a normal response in a state of insulin resistance." (PMID 34440963, 2021). "Insulin resistance is a condition characterized by decreased insulin sensitivity in peripheral tissues." (PMID 34769010, 2021). "Alongside MKP-1, hormones with antagonist effects on insulin, such as catecholamines or glucagon, and muscle wasting can also contribute to insulin resistance." (PMID 34575946, 2021). "Since hepatic insulin resistance caused by the DAG–PKCε pathway occurs at the level of phosphorylation of the insulin receptor, it is reasonable to assume that insulin-independent DNL occurs in cases of MAFLD with nutrient oversupply." (PMID 33923817, 2021). "This reduction in insulin stimulated Glut4 translocation is indicative of adipocyte dysfunction and insulin resistance, as noted in T2DM." (PMID 33498179, 2021). "In this context, we have evaluated the role of Chi3L1 in the development of insulin resistance by comparing insulin signaling in a Chi3L1 KO murine model to wild type (WT) mice C57BL/6 fed a CD." (PMID 33498326, 2021). "In T2DM, there is a progressive insulin release defect on the basis of insulin resistance, and insulin insufficiency." (PMID 34133443, 2021). "Different studies indicated that infants consuming formula milk have increased level of insulin compared to breast-fed infants, leading to a change in glucagon and insulin release, which play a role in early development of insulin resistance and T2D." (PMID 34073649, 2021). "The molecules of TG are involved in the regulation of insulin-signaling pathways through the activation of several serine/threonine kinases, which suppress insulin receptors, thus inducing peripheral insulin resistance." (PMID 33854188, 2021). "Usually, gestational diabetes mellitus (GDM) becomes apparent in the third trimester of pregnancy in patients who have pre-existing insulin resistance or have a reduced capacity to secrete insulin in response to gestational insulin resistance." (PMID 34946265, 2021). "In this scenario, considering that the mechanisms related to insulin resistance are not fully understood, it is relevant to investigate new potential regulators of insulin-stimulated glucose uptake in peripheral tissues (e.g., skeletal muscle)." (PMID 34234788, 2021). "In the context of insulin resistance, the effect of miR-92a in glucose uptake in insulin target cells such as liver, skeletal muscle or adipocytes has not been reported yet." (PMID 34416903, 2021). "Skeletal muscle cells play a vital role in whole body insulin resistance as they are a predominant site for insulin-controlled glucose uptake." (PMID 33503814, 2021). "Taken together, swertiamarin suppressed weight gain and improved obesity-related insulin resistance by activating insulin signalling." (PMID 33794740, 2021). "Previous studies have shown that glucocorticoids can inhibit insulin signaling and induce insulin resistance in different tissues including the skeletal muscle (reviewed)." (PMID 34281257, 2021). "In several pathological states, however, peripheral tissues can lose their responsiveness to insulin, a state commonly known as insulin resistance (IR)." (PMID 34046015, 2021). "Insulin resistance occurs when insulin-dependent tissues require increased concentrations of this hormone to achieve the biological effects." (PMID 34539357, 2021). "Insulin resistance is defined as an impaired biological response to insulin actions in the insulin-responsive tissues and is considered key to the mechanism of metabolic syndrome." (PMID 34442386, 2021). "Serum insulin levels increase in response to peripheral insulin resistance; however, as insulin is unable to activate the PI3K-Akt pathway it increases activation of the MAPK pathway leading to reduced production of eNOS." (PMID 34571964, 2021).